RAB27A (RAB27A, member RAS oncogene family)
Description:
The small GTPases Rab are key regulators of intracellular membrane trafficking, from the formation of transport vesicles to their fusion with membranes. Rabs cycle between an inactive GDP-bound form and an active GTP-bound form that is able to recruit to membranes different sets of downstream effectors directly responsible for vesicle formation, movement, tethering and fusion. RAB27A regulates homeostasis of late endocytic pathway, including endosomal positioning, maturation and secretion. Plays a role in cytotoxic granule exocytosis in lymphocytes. Required for both granule maturation and granule docking and priming at the immunologic synapse.
Synonyms: RAB27; RAM; GS2; HsT18676
Tractability: Small molecule: a structure with a bound ligand is known. Antibody: its Gene Ontology location is reachable by antibodies, with high confidence. PROTAC: ubiquitination databases record sites on it; its protein half-life has been measured; a small molecule that binds it is known.
Target class: Enzyme; Hydrolase
Safety:
Unwanted effects reported when the protein is acted on. In parentheses: how it was acted on, where the effect was seen, and who reports it.
leukopenia or neutropenia (source: ClinPGx)
neutropenia or leukopenia (source: ClinPGx)
Gene: Protein-coding gene on chromosome 15 (55,202,966 to 55,319,113, reverse strand). Ensembl gene ENSG00000069974.
Subcellular location: Membrane; Melanosome; Late endosome; Lysosome
Subcellular location (Human Protein Atlas): Mid piece; Principal piece
Pathways (Reactome):
Metabolism of proteins: Insulin processing; RAB geranylgeranylation
Developmental Biology: Regulation of MITF-M-dependent genes involved in pigmentation
Immune System: Neutrophil degranulation
Vesicle-mediated transport: RAB GEFs exchange GTP for GDP on RABs
Gene Ontology:
Molecular function: G protein activity; GDP binding; GTP binding; protein binding; GTPase activity; myosin V binding
Biological process: antigen processing and presentation; complement-dependent cytotoxicity; exocytosis; exosomal secretion; melanosome localization; multivesicular body organization; multivesicular body sorting pathway; positive regulation of constitutive secretory pathway; positive regulation of exocytosis; positive regulation of gene expression; positive regulation of phagocytosis; positive regulation of reactive oxygen species biosynthetic process; positive regulation of regulated secretory pathway; melanosome transport; synaptic vesicle transport; protein secretion
Cellular component: dendrite; exocytic vesicle; extracellular exosome; late endosome; lysosome; melanosome; multivesicular body membrane; apical plasma membrane; cytosol; extracellular region; Golgi apparatus; melanosome membrane; secretory granule; specific granule lumen; membrane; photoreceptor outer segment
Genetic constraint (gnomAD): Loss-of-function variants: 18 observed, 23.7 expected, observed/expected ratio (o/e) 0.76, 90% interval 0.52 to 1.13. The upper end of that interval is the gene's LOEUF score, 1.13, which puts it in group 4 of 6, group 1 being the genes least tolerant of losing a copy. Missense variants: 277 observed, 279.93 expected, observed/expected ratio (o/e) 0.99, 90% interval 0.9 to 1.09. Synonymous variants: 85 observed, 97.65 expected, observed/expected ratio (o/e) 0.87, 90% interval 0.73 to 1.04.
Gene-disease validity (ClinGen):
ClinGen rates the evidence that RAB27A causes each of these diseases.
Griscelli syndrome type 2 (autosomal recessive): Definitive.
Homologues: Orthologues: chimpanzee RAB27A (99% identical), rat Rab27a (96% identical), mouse Rab27a (96% identical), dog RAB27A (95% identical), pig RAB27A (95% identical), guinea pig RAB27A (93% identical), tropical clawed frog rab27a (87% identical), zebrafish rab27a (85% identical), rabbit RAB27A (65% identical), Caenorhabditis elegans aex-6 (59% identical), macaque RAB27A (58% identical), Drosophila melanogaster Rab27 (53% identical). Paralogues in human: RAB27B (71% identical), RAB26 (40% identical), RAB37 (39% identical), RAB3C (39% identical), RAB3A (38% identical), RAB8A (38% identical), RAB3B (38% identical), RAB3D (37% identical), RAB8B (36% identical), RAB13 (36% identical), RAB10 (35% identical), RAB11A (35% identical), and 56 more.
Diseases named in the same sentence as RAB27A in open-access papers:
RAB27A is named in the same sentence as 144 diseases in open-access papers, as found by Europe PMC text mining. Sharing a sentence is not in itself a finding about the gene and the disease. The quoted sentences say what the papers report.
melanoma (65 papers, 2009 to 2026). A malignant, usually aggressive tumor composed of atypical, neoplastic melanocytes. "The loss of Rab27a in melanoma cell lines changes the size and protein composition of released exosomes." (PMID 34283059, 2021). "In melanoma, cells expressing Rab27A produced exosomes packed with several proteins associated with a pro-invasive and motility phenotype, which upon uptake, increased the invasion capacity Rab27A-low melanoma cells." (PMID 31963599, 2020). "Prior studies in melanoma have linked Rab27a function with reduced metastatic burden, however, this effect was also associated with reduced primary tumor growth, complicating the analysis of metastatic outgrowth." (PMID 32355248, 2020). "Inhibition of exosome secretion through knockdown of Rab27A is associated with decreased tumor growth and metastasis in metastatic breast cancer and melanoma models." (PMID 30925917, 2019). "Loss of Rab27A also reduces lung metastasis in melanoma, likely through reducing the recruitment of bone-marrow derived cells in the lung." (PMID 30925917, 2019). "Interestingly, RAB27A-mediated EVs-secretion is associated with decreased melanoma patient survival." (PMID 37495566, 2023). "Our finding that secretion of these lysosomal components in melanoma cells is dependent on RAB27A, a protein that we found associated with both lysosomal populations analyzed in this study, highlights this GTPase as a potential future target to modulate SASP in aging." (PMID 36087066, 2022). "In addition, the loss of Rab27a in melanoma cell lines inhibited spontaneous metastasis in vivo, suggesting that Rab27a is important for the pro-invasive effects of exosomes produced by the wild-type cells." (PMID 34283059, 2021). "In particular, the activation of small GTPases such as CDC42, RAB17, RAC1, and RAB27A, which regulate cytoskeletal dynamics, is thought to contribute to melanoma progression and metastasis." (PMID 40594379, 2025). "Rab27A mRNA and protein were overexpressed in melanoma samples compared to normal skin or benign nevi." (PMID 39596498, 2024). "The potential role of Rab27A in the functioning of melanoma cells depends on the individual character of the cell line, but not on its basal expression, and seems to be unrelated to the secretion of sEVs." (PMID 39596498, 2024). "Our studies included three human melanoma cell lines, with various Rab27A and Rab27B expression levels, as well as their proliferative/invasive potential." (PMID 39596498, 2024). "Discrepancies in the evidence on the Rab27A requirement in sEV generation from melanoma cells are unlikely due to the methodology used to silence it." (PMID 39596498, 2024). "First, the expression of the Rab27A gene and protein was compared between melanoma cell lines using quantitative RT-PCR and Western blot, respectively." (PMID 39596498, 2024). "To investigate the function of Rab27A in melanoma cells, we used CRISPR/Cas9 technology to knock it out in A375, DMBC12, and SkMel28 cells." (PMID 39596498, 2024). "It has been found that Rab27a regulates exosome secretion in vitro and in vivo, and its overexpression facilitates the invasion and migration of melanoma cells." (PMID 37711128, 2024). "This study aimed to explore the role of Rab27A in the proliferation, migration, and invasion of various human melanoma cell lines, as well as its contribution to the secretion of small extracellular vesicles." (PMID 39596498, 2024). "Previously, Rab27A was found to control the secretion of sEVs in mouse B16-F10 and human SkMel28 melanoma cells and to promote primary tumor growth in mice." (PMID 39596498, 2024). "The MC extract also decreased the expression of MITF, CDK2, c-Met, Bcl2, and RAB27A, which had increased with melanoma cell treatment." (PMID 39684511, 2024). "It was found by others that shRNA-mediated RAB27A knockdown in metastatic WM164 melanoma cells increased the population of smaller sEVs (<100 nm)." (PMID 39596498, 2024).
melanoma (continued). "Disrupting Rab27a expression reduces exosome release, tumor growth, and metastasis in melanoma, pancreatic cancer and colorectal cancer." (PMID 36600320, 2023). "It was demonstrated that a subset of melanomas overexpressed the GTPase RAB27A, thus generating pro-invasive exosomes, which correlated with poor survival of melanoma patients." (PMID 36674479, 2023). "Overall, our results indicate that the secretion of some SASP components in senescent melanoma cells occurs, at least in part, via secretory lysosomes in a RAB27A‐dependent manner." (PMID 36087066, 2022). "Rab27a is known to serve as a regulator of melanosome trafficking and has been identified as a tumour dependency gene in melanoma." (PMID 36471254, 2022). "In melanoma, RAB27A has been identified to promote tumor growth by increasing vesicular trafficking and exosome secretion." (PMID 36371494, 2022). "RAB27A was firstly identified as an oncogenic factor in melanoma, which has been found to promote melanoma cell proliferation via activating ERK signaling pathway." (PMID 36371494, 2022). "MLPH, Rab27a, and Myo5a form ternary complexes, which play a key role in the transfer of melanoma bodies from melanocytes to neighboring keratinocytes and ultimately color the animal coat." (PMID 33466315, 2021). "Studies have shown that compared with normal skin or moles, the Ras-related protein Rab-27A (RAB27A) is upregulated in melanoma and is related to the stage of the lesion." (PMID 34485600, 2021). "Other Rab members, Rab1A, Rab5A, Rab7 and Rab27A, have been shown to be highly expressed in melanoma cells." (PMID 34401050, 2021). "miR-203 promotes melanogenesis through the CREB1/MITF/Rab27a pathway by targeting Kif5b in melanoma." (PMID 34831071, 2021). "The localization of Rab27a to melanosomes and its role in controlling the distribution of these melanin-containing compartments in melanoma cells was described almost two decades ago." (PMID 33072757, 2020). "Reduced proliferation and invasion has been described in melanoma after knockdown of Rab27a, while in breast cancer cell growth was decreased." (PMID 33282910, 2020). "This relation between high expression of Rab27a and poor prognosis has been found in many cancers, such as lung cancer, melanoma, and hepatocellular carcinoma." (PMID 33282910, 2020). "Knockdown of Rab27a has been shown to decrease the shedding of small EVs in fibrosarcoma, melanoma, prostate, and breast cancer cell lines." (PMID 33282910, 2020). "This involvement of Rab27A in pro-metastatic changes was confirmed when knock-down of Rab27A in melanoma mice models resulted in decreased metastasis formation in vivo." (PMID 31963599, 2020). "So, understanding the role of PHB on the binding of Rab27a and Mlph can give a new insight on melanoma progression and targets for treatment." (PMID 32226526, 2020). "Ras-related protein Rab-27A (RAB27A) is upregulated in melanomas compared with normal skin or nevi and is related to the advanced stage of melanomas for patients." (PMID 31355262, 2019). "Elevated expression of Rab27A has been demonstrated in tumor specimens from patients with melanoma and hepatocellular carcinoma, whereas elevated expression of Rab27B has been found in tumor specimens from patients with breast cancer." (PMID 30081925, 2018). "Rab27A knockdown by shRNA transfection suppresses in vitro cell growth of melanoma cells (WM1385 and WM1960), and suppresses in vivo tumor growth of xenografts derived from human melanoma cells (SK-Mel-28) and murine melanoma cells (B16-F10)." (PMID 30081925, 2018). "In melanoma, RAB27A serves as the target of miR-31-5p, and studies have also shown that elevated levels of RAB27A expression promote BCa proliferation and chemoresistance." (PMID 30103209, 2018). "Rab27A knockdown in murine B16-F10 melanoma cells decreases exosome secretion, prevents bone marrow education, and reduces tumor growth and metastasis." (PMID 30081925, 2018).
melanoma (continued). "Secretion of exosomes in a Rab27a-dependent manner has been revealed in melanoma and breast and bladder cancers; abnormal exosome production caused by modulating Rab27a expression can influence tumour growth, tumour metastasis and progression." (PMID 29725020, 2018). "Rab27A inhibition in melanoma cell lines reduced primary tumor growth and development of lung metastasis." (PMID 29088864, 2017). "Rab27A depletion decreased exosome production, preventing bone marrow education and reducing, tumor growth and metastasis of melanoma cells." (PMID 29088864, 2017). "In the present report, MITF regulates transcription of Rab27a as a transcription factor in melanoma cells." (PMID 27381646, 2016). "Gene expression profiling and experimental evidence indicate that during melanomagenesis, high levels of MITF in melanoma cells are associated with a vesicular trafficking signature hallmarked by high expression of Rab7, TBCD1D16, and Rab27a." (PMID 27896217, 2016). "Nevertheless, it should be noted that several known MITF target genes such as MLANA, RAB27a or SLC24A5 were weakly but significantly downregulated in all three melanoma cells, in accordance with the observations of a reduced MITF expression." (PMID 24344100, 2013). "The Epstein Barr virus-transformed, human lymphoblastoid HOM-2 cells and the human melanoma MeWo cell line, which are known to express high levels of Rab27a, were used as positive controls." (PMID 23164453, 2012). "miR-31 targets include oncogenic kinases such as SRC, MET, NIK (MAP3K14) and the melanoma specific oncogene RAB27a." (PMID 22948084, 2012). "We nominated SRC, MET, NIK and RAB27a as possible miR-31 targets in melanoma; these genes are known to play pro-tumorigenic roles in melanoma." (PMID 22948084, 2012). "Since the sEV-dependent invasive capability of melanoma cells was reported, we hypothesize that Rab27A promotes the pro-invasive character of extracellular vesicles." (PMID 39596498, 2024). "Similarly, a study from Peinado showed that a Rab27a knockdown significantly reduced exosome secretion in melanoma, hindering tumor invasion and metastasis, suggesting that Rab27a is a potential target for preventing cancer metastasis." (PMID 38495881, 2024). "Furthermore, higher levels of Rab27A mRNA were correlated with worse survival outcomes in patients with stage III melanoma." (PMID 39596498, 2024). "Furthermore, Rab27A was thought to promote the motility and proliferation of various melanoma cell lines." (PMID 39596498, 2024). "Knockdown of Rab27A or Rab27B reduced tumor growth and metastasis in murine models of melanoma." (PMID 39596498, 2024). "We speculated whether the difference in the Rab27A levels translates to various functions of melanoma cells." (PMID 39596498, 2024). "Furthermore, a reduction in metastasis in vivo was observed after the knockdown of Rab27a in melanoma mouse models, verifying Rab27a’s role in pro-metastatic alterations." (PMID 36834471, 2023). "Moreover, melanoma cells that expressed Rab27a generated exosomes that were packed with many proteins connected to melanoma development." (PMID 36834471, 2023). "By knocking out Rab27a and nSMNase2, two important exosomal biogenesis-related genes, exosomal PD-L1 was proven to suppress T-cell activity to promote multiple tumor growth, including prostate cancer and melanoma." (PMID 36834471, 2023). "Interestingly, we also found that lysosomal secretion contributes to the SASP in a RAB27A‐dependent manner in melanoma senescent cells." (PMID 36087066, 2022). "Interestingly, a subset of SASP components, including cytokines CCL2, CCL3, CXCL12, cathepsin CTSD, or the protease inhibitor SERPINE1, are secreted in a RAB27A‐dependent manner in senescent melanoma cells." (PMID 36087066, 2022). "Furthermore, Rab27a regulates exosome secretion to create a metastatic niche in melanoma and breast cancers." (PMID 35053535, 2022).